STIL (STIL centriolar assembly protein)
Diseases named in the same sentence as STIL in open-access papers (continued):
Sharing a sentence is not in itself a finding about the gene and the disease.
tumor (continued). "We tested the possibility that higher itTIL may lead to more pronounced inflammatory gene expression than sTIL as itTIL may have a crucial anti-tumor role." (PMID 31878981, 2019). "Moreover, TCGA data indicated that the relative levels of STIL mRNA transcripts in 375 GC tissues were significantly higher than that in 32 non‐tumor tissues." (PMID 31187582, 2019). "The negative association between the contraction sign and sTIL levels may be mechanistically explained by the role of dense fibrotic stroma in creating an immune-excluded tumor microenvironment." (PMID 40599582, 2025). "Among these, key genes including TMEM106C, ECT2, PSMD2, STIL, and TTK showed significant upregulation in tumor tissues, and their high expression may be closely associated with abnormal activation of tumor stem cells, cell cycle regulation, and enhanced self-renewal capacity." (PMID 40766320, 2025). "First, the ceRNA regulation axis of STIL was only predicted using online databases, thereby needing to be validated in vitro experiments; second, the potential molecular mechanisms of STIL and tumor-immune cell interactions in HCC should be confirmed in vivo experiments." (PMID 36899391, 2023). "Furthermore, CIN cancers are reported to possess T cell exclusion and infiltrating macrophages, and the centrosome is critical for cytokine production, which is necessary for the immune response, suggesting that STIL is probably involved in the tumor immune microenvironment." (PMID 36899391, 2023). "Therefore, it is tempting to speculate that STIL may have a regulatory role in tumor immunity and could be part of combination therapy approaches for enhancing the responsiveness to immune checkpoint inhibitors." (PMID 36899391, 2023). "In the present study, we demonstrated that STIL expression was significantly associated with tumor immune infiltrations and promising immunotherapy targets (such as PD-L1, CTLA-4, and TIM3), indicating that targeting STIL might increase the efficacy of immunotherapy in HCC." (PMID 36899391, 2023). "However, the role of STIL for primary cilia still needs to explore in the tumor." (PMID 35155425, 2022). "Importantly, we reveal an unexpected role of STIL in tumor metastasis." (PMID 35365182, 2022). "Importantly, we discovered a novel and unexpected role of STIL in tumor metastasis." (PMID 35365182, 2022). "Therefore, the role of STIL for primary cilia formation still needs to explore in the tumor." (PMID 35155425, 2022). "However, the presence of high sTIL levels in most residual tumours at surgery might imply that these patients might be good candidates for clinical trials evaluating adjuvant immune checkpoint inhibitors." (PMID 33742063, 2021). "Subsequently, the alterations may result in reduced sTIL in the tumor microenvironment." (PMID 33819921, 2021). "Comprehensive differential expression analysis between normal and tumor tissues revealed complex regulatory patterns of stem cell marker genes, with key genes such as TMEM106C, ECT2, PSMD2, STIL, and TTK showing significant upregulation in tumor tissues." (PMID 40766320, 2025). "Similarly, combining STIL inhibition with immune checkpoint therapies could amplify antitumor immune responses, as CIN has been linked to an increased tumor neoantigen burden, thereby enhancing tumor immunogenicity." (PMID 39727708, 2024). "Our findings indicate that the centriolar protein STIL functions not only as a key regulator in centriole duplication but also as a transcriptional coactivator that regulates EMT and stemness to promote tumor metastasis." (PMID 35365182, 2022). "Although we did not measure IL-6 secreted by SASP-positive cells, we think that high sTIL density and high iCD103 + lymphocyte levels in SASP-positive tumors would be, in part, T cell migration to tumor site by IL-6 signaling by senescent cells." (PMID 34267603, 2021). "Our findings revealed that neither iTIL nor sTIL densities in the primary tumor were correlated with those in LNMs." (PMID 39329741, 2024).
tumor (continued). "In general, ER-negative tumors are characterized by increased sTIL infiltration, CD8 + T-cells, and a higher expression of immune-related gene sets, resulting in a more inflamed tumor microenvironment, while ER-positive BC is traditionally considered to be an immunologically “cold” tumor." (PMID 37999126, 2023). "We then performed the differential analysis and correlation analysis, and only hsa-miR-204-5p was retained, with a negative correlation of STIL and significantly downregulated expression in tumor tissue than normal tissue." (PMID 36899391, 2023). "This also provides essential information that STIL, as an estrogen receptor signaling-related gene, in DLBCL, may regulate growth signals by targeting CNTFR and play a role in regulating tumor growth and development." (PMID 36531013, 2022). "Previous research also indicated that increasing STIL could promote CDK1/CCNB1 activity and indirectly participate in CCNB1 dependent proliferation in tumor cells." (PMID 35155425, 2022). "We hypothesised that high grade tumours with a combined EMT and basal phenotype with low sTIL density would be more likely to progress to MIBC and demonstrate inferior DSS." (PMID 32374509, 2020). "We hypothesised that HGT1 tumours with a propensity for EMT, high basal marker expression (at protein and mRNA level) and high sTIL expression would be more likely to progress to MIBC, with a poorer prognosis." (PMID 32374509, 2020). "Conversely, increasing STIL could promote CDK1/CYCLIN B activity and indirectly participate in CYCLIN B-dependent proliferation in tumor cells." (PMID 29352115, 2018). "The increase in sTIL and the changes in the expression of immune-related proteins did not correlate with Ki67 suppression at two weeks, a biomarker of response to ET, suggesting that these changes were not dependent on tumor response to treatment." (PMID 37450351, 2023). "In a multivariate analysis including PD-L1 expression (positive vs. negative), sTIL count (as a continuous variable), age, tumor size (T1 vs. T2/T3) NS nodal status (N− vs. N+), neither PD-L1 status (SP263 IHC) nor sTIL count was independently associated with pCR." (PMID 33558513, 2021). "Put together, this study suggests that STIL may not play a significant role in invasion of tumor; however, it could have a crucial role in early tumorigenesis." (PMID 34485108, 2021). "As previously observed for sTIL levels, increase in specific immune cell subpopulation densities was observed in HER2-enriched subtype and HR-negative tumours, but not in non-HER2-enriched PAM50 subtypes and HR-positive tumours." (PMID 33742063, 2021). "To determine the status of STIL expression in NSCLC, we examined STIL mRNA expression levels in primary LUAD (59 non-tumorous and 515 tumor samples) and primary LUSC (51 non-tumorous and 501 tumor samples) using the TCGA dataset." (PMID 39727708, 2024).
cancer (35 papers, 2013 to 2025). A tumor composed of atypical neoplastic, often pleomorphic cells that invade other tissues. "More recently, we found that STIL is involved in the regulation of cell motility via direct association with ARHGEF7 in cancer cells." (PMID 39851490, 2025). "STIL is over-expressed in multiple cancer types and is also associated with an increased metastatic potential in several cancer types." (PMID 37834064, 2023). "Overexpression of STIL leads to supernumerary centrosomes, which were linked to cancer-causing chromosomal instability (CIN)." (PMID 36899391, 2023). "Here, we probe the mechanism of oligomerization of a peptide representing the CCD of the STIL protein, a tetrameric multi-domain protein that is over-expressed in several cancers and associated with metastatic spread." (PMID 37834064, 2023). "Meanwhile, we found STIL was positively or negatively correlated with multiple cancer hallmark-related pathways across 33 cancer types by Gene Set Variation Analysis." (PMID 35155425, 2022). "It is interesting that STIL loss-of-function causes MCPH, whereas abnormally high expression of STIL triggers centriole amplification and is frequently observed in human cancers." (PMID 35365182, 2022). "In pan-cancer, STIL mutation characterization plays a weaker role in regulating STIL expression in cancers except for BLCA." (PMID 35155425, 2022). "The expression of STIL shows the most significant increase in lung and various other types of cancers, and is highly associated with patients’ survival rate." (PMID 35365182, 2022). "Up-regulated STIL was associated with poor prognosis and recurrence of cancer, promoting genomic instability and aneuploidy formation." (PMID 35155425, 2022). "Taken together, our data indicate that the mRNA and protein levels of STIL are up-regulated in lung and various other types of cancers, and that they are highly associated with poor prognosis." (PMID 35365182, 2022). "We found STIL mutated in most cancers, but the mutation frequency was generally low, ranging from 0% to 9.4%." (PMID 35155425, 2022). "SCL/TAL1 interrupting locus (STIL) regulates centriole replication and causes chromosome instability, which is closely related to malignant tumors." (PMID 36497260, 2022). "Despite few studies having shown the role of STIL in various cancers, its association with cancer prognosis stands elusive." (PMID 34485108, 2021). "STIL expression was up‐regulated in GC tissues both in our cohort and the data from the cancer genome atlas, and positively associated with T stage and poor overall survival of GC patients." (PMID 31187582, 2019). "SCL/TAL1 interrupting locus (STIL) regulates the mitotic centrosome to promote the centriolar replication and cell cycling, and is associated with malignancies." (PMID 31187582, 2019). "STIL is expressed only in proliferating cells and its expression in cancer cells is associated with metastasis and worse prognosis." (PMID 28423708, 2017). "Thus, STIL can influence the development of chromosomal instability by controlling the structure and quantity of centrosomes, which has been linked to various malignant tumors, including prostate, colon, pancreatic, and gastric cancers." (PMID 39735672, 2025). "High STIL expression was associated with worse outcomes and promoted the progression of cancers." (PMID 35155425, 2022). "Further analysis also showed that the STIL mRNA level was significantly increased in many other types of cancers and its high expression is associated with poor prognosis in patients with many cancer types." (PMID 35365182, 2022). "Further, STIL overexpression has been reported to cause chromosomal instability in cancer cells." (PMID 34485108, 2021). "Moreover, Cep131 overexpression caused excessive STIL recruitment, concurrently accumulating and stabilizing Plk4 and leading to centrosome amplification and cancer development." (PMID 31358734, 2019).
cancer (continued). "Similarly, the association of STIL upregulation with various cancers reflects a deregulation of STIL expression levels in specific tissues contributing to genomic instability." (PMID 29352115, 2018). "The role of STIL in promoting SHH signaling could be another pathway to account for its association with cancer." (PMID 29352115, 2018). "However, STIL was overexpressed in multiple cancers with PC deficiency." (PMID 37101292, 2023). "Thus, changes in STIL expression are associated with chromosome instability and even cancer." (PMID 33858425, 2021). "In addition to ASPM, the MCPH7 gene STIL has also been found to be associated with human cancer." (PMID 23472065, 2013). "The complexities of STIL’s function in the progression of cancer biology require further investigation." (PMID 39735672, 2025). "For instance, STIL expression is elevated in tissues from nasopharyngeal carcinomas, and its knockdown can prevent cancer cells from migrating and invading, accelerating the transition from the G1/S phase and apoptosis." (PMID 39718123, 2025). "This discovery adds to the growing body of evidence emphasizing STIL’s multifaceted roles in cancer biology, particularly in the context of cell migration, a critical component of cancer metastasis." (PMID 39735672, 2025). "STIL overexpression has been reported in several types of cancers, including lung, colorectal, urinary bladder, liver, and breast." (PMID 39727708, 2024). "Accordingly, STIL expression correlates with cellular proliferation and mitotic fraction of tissues, and is upregulated in multiple cancer types." (PMID 39466849, 2024). "Other studies have highlighted the additional roles of STIL overexpression in cancers other than NSCLC." (PMID 39727708, 2024). "A further 3D assay of cancer cell migration confirmed that STIL knockdown in CL1-5 cells significantly inhibited the cell migration velocity." (PMID 35365182, 2022). "Gene Ontology (GO) enrichment analysis and Gene Set Variation Analysis (GSVA) further revealed that STIL is involved in cell cycle progression, Mitotic spindle, G2M checkpoint, and E2F targets pathways across cancer types." (PMID 35155425, 2022). "The result of GSEA analysis showed that STIL-modulated genes were involved in multiple cancer pathways, including the EMT process, hypoxia, and many other signaling pathways." (PMID 35365182, 2022). "To explore the biological function of STIL, we filtered 175 co-expression genes of STIL (Pearson Correlation Coefficient ≥ 0.6) in pan-cancer levels using the GEPIA website." (PMID 35155425, 2022). "Our results showed that STIL expression was positively correlated with aneuploidy score in pan-cancer." (PMID 35155425, 2022). "We found that STIL expression was elevated, accompanied by the advanced pathological stage and histologic grade in pan-cancer level." (PMID 35155425, 2022). "Elevated expression of STIL has been reported in various cancers, such as colorectal cancer, pancreatic cancer, gastric cancer, prostate cancer, lung cancer, and nasopharyngeal carcinoma." (PMID 36497260, 2022). "The patients with high STIL expression showed worse clinical outcomes and promoted cancer recurrence." (PMID 35155425, 2022). "We found that STIL expression is up-regulated in most cancer types compared with their adjacent normal tissues." (PMID 35155425, 2022). "Intriguingly, we observed a stronger correlation between STIL mRNA expression and aneuploidy score in diploid pan-cancer samples, suggesting that genomic instability was affected by over-expressed STIL, but not a by-product of STIL CNV." (PMID 35155425, 2022). "Together, our findings indicate that STIL promotes cancer cell migration and invasion in in vitro cultured cells." (PMID 35365182, 2022). "Meanwhile, STIL over-expression was related to the progression of cancers and influenced the prognosis of cancer patients." (PMID 35155425, 2022).
cancer (continued). "STIL is integral in regulating cancer cell motility through plate oval accumulation of the ARHGEF7-PAK1 complex." (PMID 36531013, 2022). "We found STIL expression was higher in most cancer types compared with the STIL expression in all normal tissues." (PMID 35155425, 2022). "In the cell lines representing different malignancy degrees of these two cancer types, STIL protein expression in PC3 and 769-P showed the highest levels." (PMID 35155425, 2022). "In pan-cancer levels, STIL copy number represented a positive correlation with STIL mRNA expression." (PMID 35155425, 2022). "High STIL expression was accompanied by advanced pathological stage and malignancy degree of cancers, revealing STIL act as an oncogene can promote cancer progression." (PMID 35155425, 2022). "IHC of STIL protein in cancer tissues showed a very high cytoplasm-specific staining compared to normal tissue." (PMID 34485108, 2021). "Their host genes had been described in individual studies with regard to their roles in either PCa progression (e.g., CRIM1, NEAT1, and STIL) or other cancers (e.g., LPP and RHOBTB3)." (PMID 33105568, 2020). "In developing human cancer cells, STIL is localized to the pericentriolar region of the centrosomes, where it regulates in spindle pole positioning as well as centriole formation and duplication." (PMID 31044090, 2019). "While ample proof of STIL functions in cancer can be found in the literature, evidence also exists that STIL is involved in the development and function of the nervous system." (PMID 31044090, 2019). "Instead, we observed that several indirect interactions disappear in the “cancer” network, namely three indirect regulations connecting STIL protein to CCNA2, CCNE1 and CDK1." (PMID 29370181, 2018). "In this study, we found that RFX5 was highly expressed in HCC and could activate STIL expression by regulating glycolysis to promote cancer cell stemness." (PMID 39718123, 2025). "Moreover, the level of STIL expression in cancer cells was markedly elevated compared to normal cells (16HBE), particularly in H23 and H1299 cells." (PMID 39735672, 2025). "Recently, we reported that ARHGEF7 and PAK1 together associated with STIL, one of the centrosomal proteins, at the lamellipodia protrusion of motile cells and that STIL is involved in the ARHGEF7-mediated activation of cytoskeletal remodeling in cancer cells." (PMID 39851490, 2025). "In contrast, excess STIL promotes cancer cell invasion and migration by triggering the EMT." (PMID 39735672, 2025). "Overexpression of STIL mRNA and protein has been found in many cancer types." (PMID 39466849, 2024). "Several studies have suggested that STIL overexpression may serve as a potential therapeutic target for cancer." (PMID 39727708, 2024). "Overall, this study offers a basis for understanding the structural molecular biology of the STIL protein, and how it might be targeted to discover anti-cancer reagents." (PMID 37834064, 2023). "In addition, both studies found an association between histologic ILC variants and lymphocyte infiltration, as the alveolar histotype was found more often to be sTIL-negative, while mixed ILC carcinomas were mostly sTIL-enriched." (PMID 37296857, 2023). "Interestingly, the STIL DNA methylation level showed significant down-regulation in multiple cancer types." (PMID 35155425, 2022). "Interestingly, we found STIL showed a consistently positive correlation with three pathways across 33 cancer types, including mitotic spindle (Path 30), G2M checkpoint (Path 18), and E2F targets pathways (Path 13)." (PMID 35155425, 2022). "Importantly, we demonstrate that hypoxia is a new factor contributing to STIL upregulation in cancers." (PMID 35365182, 2022). "We then analyzed the correlation between DNA methylation and STIL expression across cancer types." (PMID 35155425, 2022). "The GEO datasets were further analyzed to verify the STIL expression alteration in cancers." (PMID 35155425, 2022).